FASN (fatty acid synthase)
Diseases named in the same sentence as FASN in open-access papers (continued):
Sharing a sentence is not in itself a finding about the gene and the disease.
tumor (continued). "Contrary to normal cells, which prefer exogenous fatty acids, tumor cells depends on de novo fatty acid synthesis from tricarboxylic acid cycle-derived precursors catalyzed by fatty acid synthase (FASN)." (PMID 29245936, 2017). "Increased levels of enzymes such as fatty acid synthase (FASN) involved in cell lipid production have shown to be essential for the survival of a number of cultured tumor cell lines." (PMID 28966808, 2017). "Lipogenic enzymes such as fatty acid synthase (FASN) are commonly overexpressed or show enhanced activity in neoplastic disease." (PMID 29088795, 2017). "Over-expression of FASN has been shown to result in changes of membrane composition and to modulate lipid rafts in tumor cells." (PMID 27602772, 2016). "In conclusion, we demonstrated that FASN expression is primarily downregulated by miR-15a and miR-16-1 in mammary cells and FASN is one of the major targets of these two tumor suppressive microRNAs." (PMID 27713175, 2016). "The FASN inhibitor c75 decreased cell viability in control cells, underscoring the need for de novo lipid biogenesis in highly proliferative tumor cells." (PMID 27223259, 2016). "FASN immunoreactivities were detected in the cytosol in tumor cells, while those of Sox2 were confined to the nuclei." (PMID 26808816, 2016). "The results indicate that FASN expression is enhanced in xenograft tumour cells under HFD conditions, and that it is regulated by PI3K, MAPK and AMPK signalling pathways." (PMID 26878389, 2016). "Tumor uptake of radiolabeled acetate not only reflects the expression of cytosolic acetyl-coenzyme A (CoA) synthetase, but also the fatty acid synthase." (PMID 26754531, 2016). "Studies show that FASN inhibition induces cell-cycle arrest, leading to decrease in tumor cell proliferation and apoptosis." (PMID 27579768, 2016). "FASN is an attractive therapeutic target as it regulates neoplastic transformation, metastasis as well as angiogenic pathways manipulating tumor vascularity and cell proliferation." (PMID 27072583, 2016). "In this study, the HFD enhanced tumour growth and FASN expression in the LNCaP xenograft mice, as expected." (PMID 26878389, 2016). "More importantly, we found the FASN positive-stained cells were dramatically reduced in tumor tissues obtained from the cerulenin-injected mice compared to the vehicle-injected control mice." (PMID 27765901, 2016). "STRING analysis confirmed protein-protein-interactions of regulated genes and Western immunoblotting of fatty acid synthase, serine hydroxyl-methyltransferase 1, arginine 1 and hexokinase 2 showed tumor specific induction." (PMID 27602772, 2016). "Our results corroborate recent studies showing that blocking FASN-driven lipid synthesis efficiently overcomes tumor regrowth and metastasis after antiangiogenic therapy withdrawal." (PMID 27223424, 2016). "Our results show that levels of P-gp and other molecules involved in drug resistance such as FASN and Cav-1 are elevated in tumor excised from obese mice treated or untreated with DTIC as compared to mice kept on ND." (PMID 27980732, 2016). "We have earlier reported that increased level of FASN and caveolin (Cav)-1 contributes to the enhanced tumor growth in obese mice." (PMID 27980732, 2016). "Although FASN level is low in normal tissues, its expression level is higher in several tumor and cancer cells (e.g., colorectal cancer and endometrial cancers)." (PMID 26437434, 2015). "Relative to that in healthy fallopian tube tissue, tumor tissues had 1.8-fold average FASN protein overexpression; cell lines and primary cultures had 11-fold–100-fold mRNA and protein overexpression." (PMID 25947066, 2015). "Because of the generally greater FASN inhibition and anti-tumor effects achieved by cerulenin versus C75, experiments regarding cisplatin resistance were performed only with the former FASN inhibitor." (PMID 25947066, 2015).
tumor (continued). "Drugs targeting fatty acid biosynthesis pathway include FASN inhibitors such as cerulenin, C75, orlistat with anti-tumor activity, which were tested in vitro and in mice models." (PMID 26437434, 2015). "The tissue arrays did not contain sufficient stage III and IV tumor samples to correlate expression of Mov10 and FASN with tumor stage." (PMID 26029828, 2015). "Second, FASN overexpression has been described in tumor cell lines in which chemotherapy resistance was induced by culture in drug-containing media." (PMID 25947066, 2015). "The expression of PLIN1 (p < 0.001), FABP4 (p = 0.029), CPT-1A (p = 0.001), ACOX-1 (p < 0.001), and FASN (p < 0.001) differed significantly among these tumor subtypes." (PMID 25751270, 2015). "Some of these tumor samples contained both high- and low-Mov10-expressing regions and the levels of FASN staining in each region was the inverse of the level of Mov10." (PMID 26029828, 2015). "Relative to that in fallopian tube tissue, FASN protein expression – by IRS = immunoreactive scoring - was on average elevated 1.6-fold in LMP/G1 tumor samples and 1.8-fold in G2/G3 tumor samples." (PMID 25947066, 2015). "Strong FASN overexpression was detected in the majority of tumor samples compared to healthy fallopian tube tissue samples." (PMID 25947066, 2015). "Increased expression of FASN was shown in tumors and correlated with decreased survival and increased disease recurrence in several tumor types." (PMID 24979135, 2014). "Aside from FASN expression differences between hormone-dependent and hormone-independent cell lines, FASN levels also increased with each successive tumor stage." (PMID 24778702, 2014). "The chemopreventive effects of CAPE and CAPPE were in part associated with the suppression of the PCNA, FASN and MMP-9 proteins in these tumor-bearing animals." (PMID 24960186, 2014). "Although the mechanisms for tumor related FASN overexpression are still unclear, two main mechanisms have been proposed." (PMID 24778702, 2014). "Other studies of Coix seed extract show that it can inhibit tumor cell mitosis at G2/M phases, induce tumor cell apoptosis, inhibit tumor angiogenesis, and also upregulate FASN/Apo-1 gene expression and downregulate Bcl-2 gene expression of tumor cells." (PMID 24778702, 2014). "Elevated Nac1 also contributes to tumour aggressiveness and drug-resistance by increasing the levels of FASN (fatty acid synthase) and thereby modulating fatty acid metabolism." (PMID 24702277, 2014). "Several studies have shown that tumor cells are capable of reactivating de novo lipid synthesis and expressing elevated levels of fatty acid synthase (FASN) which is regulated by SREBP-1." (PMID 24614076, 2014). "Ninety-eight percent of patient 8’s tumor cells expressed fatty acid synthase, and 50% of patient 10’s tumor cells expressed insulin-like growth factor." (PMID 25126591, 2014). "Over-expression of FASN results in a significant increase of tumor burden in peritoneal dissemination, accompanied by augment in cellular colony formation and metastatic ability." (PMID 24979135, 2014). "Despite the presence of high levels of circulating dietary FAs, FASN plays a central role in tumor cell development and survival." (PMID 25313139, 2014). "CAPE and CAPPE further significantly inhibited the expression of FASN, cyclin D1, cyclin E, Cdk4 and c-myc proteins of tumor tissues in an in vivo animal study." (PMID 24960186, 2014). "The finding that elevated PEMT expression in NSCLC tissue predicts shorter patient survival independently of increased FASN or LPL activities further strengthens the evidence that lipid mobilization is required to sustain tumor growth." (PMID 24932311, 2014). "Cerulenin and C75, which target the ketoacyl synthase domain of FASN, were reported as effective small molecular inhibitors of FASN activity in tumor cells." (PMID 22886728, 2013).
tumor (continued). "FASN level correlates with tumor progression and it play an important role in tumor growth, survival and development of drug resistance." (PMID 23613870, 2013). "Tumor tissue samples were characterized by histopathology and immunohistochemistry for Glut1, FASN, Ki67, and CD34." (PMID 22875335, 2013). "Taken together, these data suggest an additional mechanism of FASN inhibition; that is, FASN inhibition disrupts tumor progression via suppression of arachidonic acid and androgen production." (PMID 23741342, 2013). "We revealed that tumor uptake of radiolabeled acetate reflected the FASN expression levels and sensitivity to FASN-targeted therapy with orlistat in vitro and in vivo." (PMID 23741342, 2013). "We further examined sensitivity of FASN-targeted therapy with orlistat in each tumor xenograft in vivo." (PMID 23741342, 2013). "Taken together with the fact that FASN inhibition can suppress multiple important steps in tumor progression, FASN-targeted therapy can be an effective treatment if uptake of radiolabeled acetate indicates subject tumors to be “responsive”." (PMID 23741342, 2013). "Inhibition of FASN by C75 and orlistat induces cell death in a variety of tumor cell lines and effectively inhibits the growth of prostate and breast carcinoma xenografts in mice." (PMID 22886728, 2013). "We and others have demonstrated that exposure of tumor cells to orlistat, a FASN inhibitor; can manifests tumor-specific cytotoxicity." (PMID 24349275, 2013). "Next, to examine the mechanisms how FASN inhibition affects tumor progression, we adopted FASN knockdown LNCaP cells obtained by shRNA transduction." (PMID 23741342, 2013). "The constitutive over-expression of FASN in tumor cells is largely due to dysregulation of signal transduction mechanisms that down-regulate FASN expression in normal cells." (PMID 22886728, 2013). "Levels of FASN expression of each tumor xenograft was confirmed prior to the experiment, which showed similar tendency to the in vitro study." (PMID 23741342, 2013). "FASN is robustly expressed in many solid tumors and early tumorigenic lesions in the colon and supports tumor cell proliferation and survival through enhanced lipogenesis and anti-apoptosis." (PMID 23056418, 2012). "As we have previously reported, this treatment regimen markedly prolongs survival of tumor-bearing mice and is associated with reduced E2F1 and FASN expression and with diminished proliferation in the tumors, as indicated by reduced levels of cyclin D2." (PMID 22407012, 2012). "In some malignant cells, chemical or genetic silencing of FASN induces cell death in vitro and delays tumor growth in vivo." (PMID 21406729, 2011). "With respect to ex vivo FASN enzymatic activity, however, the experimental tumours that had a response to G28UCM (11T and 12T) showed a decrease of 30.5 ± 15% compared with the control 4C tumour." (PMID 22177475, 2011). "The long term suppression of fatty acid synthase would contribute to reduced tumor burden seen in this model." (PMID 20205934, 2010). "At low concentrations, FASN inhibitor also sensitized tumor cells with FASN overexpression to chemotherapeutic agents." (PMID 20508725, 2010). "The first generation of FASN inhibitors, including C75 and Orlistat, potently inhibited tumor growth in a mouse xenograft model but the adverse effects associated with these drugs prevented their further consideration for clinical applications." (PMID 20508725, 2010). "For example, the ranks of tumor genes FASN and TACSTD1 are 15 and 6 by WROM and 13 and 6 by UWROM while the ranks of these genes are 72 and 289 by WSMD and 231 and 413 by UWSMD." (PMID 19891778, 2009). "As with these intracellular signalling molecules, extracellular tumour microenvironmental stresses play an important role in tumour-related FASN expression." (PMID 19352381, 2009). "FASN and tumour-related survival signals are mutually regulated, and FASN controls HER2-dependent signalling." (PMID 19352381, 2009).
tumor (continued). "It has been found that cerulenin, a natural fungal inhibitor of FASN, specifically targets and suppresses tumor cell growth, with little effect on the surrounding normal tissues." (PMID 18523653, 2008). "Six candidates, from whom antibodies for IHC analyses are available, were analysed in detail in a large tumour collection using tissue microarray technology: FASN, BARK1, PP1α, PP2A, NM23-H1, and MYC." (PMID 17146477, 2007). "MYC, BARK1, and FASN protein expression were statistically significant predictors of Gleason score (P<0.001, P=0.023, P=0.036), representing tumour differentiation." (PMID 17146477, 2007). "Consequently, elevated palmitic acid levels in turn reinforce SMAD4 palmitoylation, establishing a self-amplifying SMAD4 palmitoylation-FASN-palmitic acid positive feedback loop that drives PDAC tumor growth." (PMID 41885390, 2026). "FASN in the tumor microenvironment is regulated directly or indirectly by several upstream molecules, and this regulation determines the levels of fatty acids and other nutrients in the tumor microenvironment, influencing tumor cell metabolism and growth." (PMID 40936898, 2025). "Additionally, FASN modulates cell cycle regulation by stabilizing p27^Kip1 through Skp2 suppression, linking lipid metabolism to tumor cell cycle arrest." (PMID 40370434, 2025). "FASN silencing reduced spheroid formation, in vivo tumor growth, and CD133+CD44+ cells." (PMID 40901481, 2025). "Besides, the IHC staining intensity of FASN, the terminal enzyme in de novo FA synthesis, was shown to be positively correlated with tumor staging and distant metastasis in 120 RCC patients." (PMID 40933888, 2025). "The combination of FASN inhibitors and cisplatin also decreased fatty acid metabolism, glutamine metabolism, nucleotide and glutathione biosynthesis, and fatty acid β-oxidation in tumor cells, resulting in cell cycle arrest and extensive cell death." (PMID 39757995, 2025). "In addition, adverse conditions such as hypoxia and acidosis in the tumor microenvironment have also been reported to lead to the overexpression of FASN." (PMID 41421797, 2025). "Furthermore, in more aggressive DLBCL cases, lymphoma cells utilized FASN as a tumor escape tool to enhance their survival prospects." (PMID 41462004, 2025). "Beyond its role in tumor growth, FASN is also a key metabolic factor in immune evasion." (PMID 40552664, 2025). "There are also reports that FASN impedes the anti-tumor immune process in OC." (PMID 41421797, 2025). "Furthermore, ZDHHC21, functioning as a tumor suppressor, interacts with FASN and mediates its palmitoylation, leading to decreased FASN protein stability and inhibition of FA synthesis, thereby suppressing DLBCL cell growth." (PMID 40814339, 2025). "FASN expression was significantly correlated with tumor differentiation and survival." (PMID 40148316, 2025). "Moreover, the tumor number was positively correlated with FASN expression and Oil red O result, but was negatively correlated with MUC‐2 and ZO‐1 expression." (PMID 40433987, 2025). "Notably, blocking fatty acid synthase (FASN) obviously promoted the efficacy of focal RT in tumor-bearing mice." (PMID 40102409, 2025). "Aberrant FASN expression disrupts fatty acid metabolic homeostasis, triggers lipid dysmetabolism, and contributes to pathological processes including tumor proliferation and energy reprogramming by supplying abnormal lipid substrates, thereby impacting metabolic microenvironmental homeostasis." (PMID 41226659, 2025). "Preclinical studies have confirmed that combining FASN inhibitors with anti-PD-L1 antibodies significantly suppresses tumor growth, while SCD1 inhibition not only enhances CD8 T cell infiltration but may also improve response to PD-1 blockade therapy." (PMID 40533802, 2025).
tumor (continued). "MiR-195-5p, potentially sponged by five candidate MR-circRNAs, acts as a tumor suppressor in malignant MNG, by directly targeting the upregulated fatty acid synthase (FASN), whose role in de novo lipogenesis is critical for both the proliferation and survival of tumor cells." (PMID 40943185, 2025). "Furthermore, FASN inhibitors can reverse the immunosuppression in the tumor microenvironment by upregulating cytotoxicity markers in NK cells and CD8+ T lymphocytes." (PMID 39757995, 2025). "FASN catalyzes the conversion of malonyl-coenzyme A (CoA) and acetyl-CoA into palmitic acid, a 16-carbon chain saturated fatty acid that acts as a precursor of fatty acids, thus giving tumor cells a proliferative advantage." (PMID 40133809, 2025). "Measurement of tumor volume and weight revealed that FASN knockdown inhibited tumor growth in vivo." (PMID 40148316, 2025). "Human protein array analyses identified cellular targets of XON9, such as solute carrier family 3 member 2 (SLC3A2), annexin A5 (ANXA5), fatty acid synthase (FASN) or reticulon 4 (RTN4) involved notably in tumor progression, angiogenesis, cell growth or apoptosis." (PMID 41009747, 2025). "FASN activity is increased in tumor cells, and an elevation of O-GlcNAcylation is usually observed during carcinogenesis; we thus suggested that O-GlcNAcylation at T980 can be required to assist the pro-oncogenic features of FASN." (PMID 40684943, 2025). "To understand the causal role played by FASN in colonic tumorigenesis in our nATF6IEC mouse model, we exposed fl/fl and tg/tg SPF mice to biweekly intraperitoneal (i.p.)injections of the FASN inhibitor C75 from the age of 3 weeks (pre-tumour time point) until 12 weeks (tumour time point)." (PMID 40890536, 2025). "It is necessary to validate the activation of the USP38/FASN signaling pathway in more tumor types." (PMID 40936898, 2025). "The FASN/USP2/VCP axis effectively promotes autophagy in tumor cells." (PMID 40936898, 2025). "Moreover, Oil Red O staining showed that the levels of lipid droplets in the tumor tissues from sh-FASN group were lower than those in the tumor tissues from sh-NC group." (PMID 40148316, 2025). "Combining FASN inhibitors (orlistat/TVB-2640) with anti-PD-L1 antibodies suppresses tumor growth." (PMID 40977744, 2025). "Additionally, in vivo experiments revealed that FASN knockdown significantly inhibits tumor growth and the spread of CRC cells to the lungs." (PMID 40148316, 2025). "The expression and activity of many key regulators involved in lipid metabolism, such as AMP-activated protein kinase (AMPK), fatty acid synthase (FASN), and acetyl-CoA carboxylase (ACC), are associated with energy reserves and rapid proliferation of tumor cells." (PMID 39402211, 2025). "CD9 expression showed a strong spatial correlation with FASN expression, indicating these genes may play roles in creating tumor microenvironments that facilitate the transition to invasive cancer." (PMID 40163697, 2025). "FASN inhibitor TVB2640 also effectively suppresses tumour growth in the KAR mice." (PMID 40621620, 2025). "FASN deficiency promotes CD8+ T-cell infiltration and tumor killing." (PMID 40977744, 2025). "Moreover, elucidating how FASN inhibition contributes to tumor growth suppression in vivo is essential, warranting studies using tumor-bearing and FASN knockdown mouse models." (PMID 40733158, 2025). "Immunohistochemistry, immunofluorescence, and Western blot were used to further confirm whether the expression of fatty acid synthase (FASN) was significantly increased in tumor tissues." (PMID 41480378, 2025). "As a FASN inhibitor, orlistat exhibits a synergistic anti-tumor effect with sorafenib at low doses." (PMID 40069732, 2025). "Tumor cells typically maintain de novo lipid synthesis and membrane biogenesis by upregulating the expression of various metabolic enzymes, such as fatty acid synthase (FASN), acetyl-coa carboxylase (ACC), and ATP-citrate lyase (ACLY)." (PMID 41236698, 2025).